ZNF155 (zinc finger protein 155)
Description:
May be involved in transcriptional regulation.
Synonyms: pHZ-96
Tractability: PROTAC: ubiquitination databases record sites on it.
Gene: Protein-coding gene on chromosome 19 (43,967,862 to 43,998,326, forward strand). Ensembl gene ENSG00000204920.
Subcellular location: Nucleus
Subcellular location (Human Protein Atlas): Cytosol; Nucleoplasm
Pathways (Reactome):
Gene expression (Transcription): Generic Transcription Pathway
Gene Ontology:
Molecular function: protein binding; DNA-binding transcription factor activity; DNA-binding transcription repressor activity, RNA polymerase II-specific; sequence-specific DNA binding
Biological process: negative regulation of transcription by RNA polymerase II; regulation of DNA-templated transcription
Cellular component: nucleoplasm; nucleus
Genetic constraint (gnomAD): Loss-of-function variants: 14 observed, 12.02 expected, observed/expected ratio (o/e) 1.16, 90% interval 0.77 to 1.76. The upper end of that interval is the gene's LOEUF score, 1.76, which puts it in group 6 of 6, group 1 being the genes least tolerant of losing a copy. Missense variants: 586 observed, 649.17 expected, observed/expected ratio (o/e) 0.9, 90% interval 0.84 to 0.97. Synonymous variants: 206 observed, 222.77 expected, observed/expected ratio (o/e) 0.92, 90% interval 0.82 to 1.04.
Homologues: Orthologues: chimpanzee ZNF155 (98% identical), dog ZNF227 (52% identical). Paralogues in human: ZNF223 (70% identical), ZNF230 (70% identical), ZNF222 (69% identical), ZNF233 (42% identical), ZNF285 (38% identical), ZNF214 (36% identical), ZNF527 (35% identical), ZNF34 (34% identical), ZKSCAN7 (33% identical), ZNF572 (33% identical), ZNF852 (33% identical), ZNF287 (33% identical), and 38 more.
Diseases named in the same sentence as ZNF155 in open-access papers:
ZNF155 is named in the same sentence as 1 disease in open-access papers, as found by Europe PMC text mining. Sharing a sentence is not in itself a finding about the gene and the disease.
ZNF155 shares sentences with these, for which no sentence is quoted: breast carcinoma (1 paper).